FBXO32 (F-box protein 32)
Diseases named in the same sentence as FBXO32 in open-access papers (continued):
Sharing a sentence is not in itself a finding about the gene and the disease.
cardiac hypertrophy (31 papers, 2008 to 2025). "Gain and loss of function studies in mice have shown a role of FBXO32 in muscle atrophy, pathological cardiac hypertrophy, and cardiomyopathy due to premature cardiac aging." (PMID 34272480, 2021). "Under stress conditions, FBXO32 is also a negative regulator of pathological cardiac hypertrophy, which is associated with degradation of calcineurin A." (PMID 26753747, 2016). "The protein encoded by FBXO32, also known as atrogin-1 and MAFbx, is an E3 ligase that is expressed selectively in skeletal muscles and cardiomyocytes and plays a critical role in muscle atrophy, as well as in the development of cardiac hypertrophy and atrophy." (PMID 26768247, 2016). "Fbxo32 (Atrogin-1), a key regulator of cardiac hypertrophy, was identified by our screening approach and showed a 1.21-fold increase in mean cell size upon siRNA-mediated depletion at basal conditions." (PMID 36969608, 2023). "FBXO32 is a muscle-specific ubiquitin-E3 ligase also known as Atrogin-1/MAFbx, that regulates Akt-dependent cardiac hypertrophy (physiological) and calcineurin A-dependent (pathological) cardiac hypertrophy in mice." (PMID 34272480, 2021). "Three genes linked to inhibition of cardiac hypertrophy were upregulate, viz., DKK3 (Dickkopf-3), FBXO32 (encoding E3 ligase, Fbxo32), and GADD45B, which blocks MKK7-induced JNK activation." (PMID 29556499, 2018). "FBXO32 negatively regulates physiological cardiac hypertrophy by enhancing the activity of Forkhead transcription factors." (PMID 26753747, 2016). "The promotion of ubiquitination activities via expression of Atrogin-1 (FBXO32) and repression of calcineurin A apparently leads to inhibition of cardiac hypertrophy." (PMID 26930585, 2016). "FBXO32 regulates the stability of calcineurin A, an important mediator of cardiac hypertrophy (for Review)." (PMID 26753747, 2016). "Consistent with the role of FBXO32 in heart failure, toxicity annotation in IPA showed that cardiac hypertrophy ranked number one in the mutant FBXO32 heart, followed by mitochondrial dysfunction." (PMID 34272480, 2021).
diabetes (31 papers, 2010 to 2026). "Fbxo32 increased more significantly in the diaphragm tissue of DB mice after MV, which provided further evidence that MV induced more severe diaphragm dysfunction and atrophy in mice with diabetes versus healthy mice." (PMID 38784031, 2024). "Hence, abnormal ROS promoted the Akt/FOXO-3a/FBXO-32-dependent regulation of BK channel degradation in diabetes mellitus." (PMID 32547406, 2020). "Thus, the PI3K/Akt signaling regulated the BK-β1 subunit expression via FOXO-3a/FBXO-32 in diabetes mellitus." (PMID 32547406, 2020). "FOXO family proteins play a vital role in the development of muscle atrophy by activating the ubiquitin-mediated proteolysis pathways including the regulation of FBXO32/Atrogin-1 and TRIM63/MuRF1, and dependently regulate BNIP3L and GABARAPL1 in a STZ-diabetes model." (PMID 32806520, 2020). "The results from the UALCAN database further confirmed the GSE21501 data that FBXO32 was closely relevant in the lymphatic metastasis of PDAC as well as showed that FBOX20 expression was relatively lower in PDAC patients with diabetes, compared with PDAC patients without diabetes." (PMID 35046938, 2021).
cardiomyopathy (14 papers, 2016 to 2025). A disease of the heart muscle or myocardium proper. "In another study, FBXO32-knockout mice showed intracellular protein accumulation and cardiomyocyte apoptosis, causing cardiomyopathy and premature death via impaired autophagy." (PMID 36344977, 2022). "Our results suggest that the cardiomyopathy induced by the FBXO32 mutation results from the impairment of several pathways converging to ER stress and apoptosis." (PMID 34272480, 2021). "Our findings highlight a critical mechanism underlying the pathogenesis of DCM and suggest that targeting CHOP or perhaps ATF2 should be considered as an approach for the treatment of DCM and in particular the cardiomyopathy due to the FBXO32 mutation." (PMID 34272480, 2021). "Together, these results show robust activation of the ER-stress-associated apoptosis pathway in the mutant FBXO32 hearts, suggesting a prominent role of this pathway in the cardiomyopathy caused by the FBXO32 mutation." (PMID 34272480, 2021). "Apoptosis is a well-known contributor to heart failure and collectively, our results implicate that the FBXO32 mutation activates at least two CHOP-mediated apoptosis pathways leading to premature cardiomyopathy and heart failure." (PMID 34272480, 2021). "Altogether, the induction of CHOP, GADD34, and a plethora of CHOP target genes in mutant FBXO32 hearts, is indicative of elevated ER-stress and suggest that the ER-stress pathway is a major contributor to the cardiomyopathy caused by the FBXO32 mutation." (PMID 34272480, 2021). "Our results showed a prominent induction of CHOP protein in mutant FBXO32 hearts, which did not occur in control and IDC hearts, suggesting a critical role of CHOP in the cardiomyopathy caused by the FBXO32 mutation." (PMID 34272480, 2021). "Assessment of FBXO32 molecular targets in cardiac tissue of the affected individual suggests that the FBXO32 mutation causes cardiomyopathy through impaired expression of selective proteins of the autophagy system." (PMID 26753747, 2016). "FBXO32, which encodes a muscle-specific ubiquitin ligase, has been implicated in the pathogenesis of cardiomyopathy through the ubiquitin proteasome system (UPS)." (PMID 26768247, 2016). "Most recently, a role of FBXO32 in myocardial aging was reported as FBXO32 deficiency led to cardiomyopathy over time due to impaired autophagy." (PMID 26753747, 2016). "The recent finding that FBXO32 deficiency causes an aging-related cardiomyopathy in mice due to impaired autophagy provided the first direct link between FBXO32 and the autophagy system." (PMID 26753747, 2016). "Thus, the defect in the last step of the autophagic pathway observed in the human hearts with the FBXO32 mutation, which is also recapitulated in aging FBXO32-deficient mice, is likely to contribute to the cardiomyopathy." (PMID 26753747, 2016). "Thus, while our results point toward ATF2 as a novel FBXO32 target, further experiments are required to establish the direct link between ATF2 and the cardiomyopathy caused by the FBXO32 mutation." (PMID 34272480, 2021). "Although we cannot exclude the possibility that differences may occur at the protein level, this suggests that the extrinsic apoptosis pathway plays a minor role in FBXO32-mediated cardiomyopathy." (PMID 34272480, 2021). "Acting as a cardiac ubiquitin ligase, mutated FBXO32 could perturb the degradation of target proteins in the UPS, the impairment of which has been observed in cardiomyopathy." (PMID 26768247, 2016). "The immunohistochemical analysis of the FBXO32 protein showed cytoplasmic staining with reduced expression in the left ventricle of the index case in comparison to a control myocardial specimen from a non-cardiomyopathy case." (PMID 26768247, 2016).
cardiomyopathy (continued). "ER stress, abnormal CHOP activation and CHOP-induced apoptosis with no UPR effector activation are found to underlie the FBXO32 mutation induced cardiomyopathy, suggesting an alternative pathway that can be considered to develop new therapeutic targets for its treatment." (PMID 34272480, 2021). "In addition, FBXO32-knockout mice manifest with cardiomyopathy." (PMID 26768247, 2016). "Therefore, based on the cardioprotective role of GRP78 in vivo, it is reasonable to speculate that the downregulation of GRP78 protein observed in FBXO32 mutant hearts contributes to the cardiomyopathy rather than represents a secondary compensatory effect." (PMID 34272480, 2021).
breast carcinoma (11 papers, 2017 to 2024). "FOXK2 regulates the downstream gene FBXO32 in breast cancer and then activates ribosome‐associated pathways to promote tumor cell proliferation." (PMID 39552461, 2024). "We found that FBXO32 is the most likely downstream gene in the breast cancer cell line MCF‐7, except for the FOX family." (PMID 39552461, 2024). "In breast cancer, FBXO32 mediates CtBP1 ubiquitination and nuclear translocation to promote epithelial-to-mesenchymal transition (EMT)." (PMID 38643215, 2024). "It is noted that FBXO32 is a specific stress response gene that activates the protective NF-κB pathway of breast cancer cells upon challenge with genotoxic and inflammatory stress." (PMID 33585183, 2020). "The only mRNAs from our studies that was not linked to an outcome in breast cancer is Fbxo32 also called Atrogin1." (PMID 34990474, 2022). "Furthermore, FBXO32 inhibited breast cancer oncogenesis and progression via interacting with KLF4 for its ubiquitination and degradation, a critical factor for cell fate decisions." (PMID 35046938, 2021). "DZNep also upregulates FBXO32 to activate FBXO32-mediated apoptosis of breast cancer cells." (PMID 34122074, 2021). "Moreover, depletion of FBXO32 in the mesenchymal breast cancer cell line (MDA-MD-231) led to a significant reduction in their migration and invasion potential." (PMID 29142217, 2017). "In addition, FBXO32 targets IκBα proteasome degradation in breast and human kidney transformed cells, while FBXO32 contributes the activation of NF-κB pathway in various tissues, while also exacerbating inflammation and genotoxic stress in breast cancer MCF7 cells." (PMID 33585183, 2020). "Moreover, in the same study, the expression of FBXO32 was elevated in breast cancer cells with invasive properties (MDA-MB-231 cells), and depletion of FBXO32 in a xenograft mouse model suppressed tumor growth and metastasis." (PMID 30999935, 2019). "Note that FBXO32 was reported to bind and regulate CTBP1 in breast cancer cells, but we identified CTBP1 neither in the proteomic analyses nor in classical co-immunoprecipitation experiments (not shown)." (PMID 33462405, 2021).
chronic kidney disease (10 papers, 2018 to 2022). Impairment of the renal function secondary to chronic kidney damage persisting for three or more months. "Although the miR-27a-–FoxO1 interaction is not validated in skeletal muscle cells, the overexpression of miR-27a in mice with chronic kidney disease attenuated muscle loss, improved grip strength, and decreased the expression of FoxO1, Trim63, and Fbxo32 proteins." (PMID 31013615, 2019).
heart failure (10 papers, 2011 to 2025). Inability of the heart to pump blood at an adequate rate to meet tissue metabolic requirements. "We previously reported a missense homozygous mutation in FBXO32 (MAFbx, Atrogin-1) causing advanced heart failure by impairing autophagy." (PMID 34272480, 2021). "To understand the mechanisms by which the FBXO32 mutation causes early-onset heart failure, we compared global gene expression in control, mutant FBXO32, and IDC hearts." (PMID 34272480, 2021). "In a large consanguineous family from Saudi Arabia, we discovered that patients who are homozygous for the FBXO32-Gly243Arg mutation develop advanced heart failure." (PMID 34272480, 2021). "To gain further insights into the mechanisms by which the FBXO32 mutation causes heart failure, we performed a genome-wide expression profiling in the heart of one patient carrying the FBXO32 mutation (patient IV.7), which was the only explanted heart available at the time of the analysis." (PMID 34272480, 2021). "FBXO32 signaling correlates with MuRF-1 in the heart and skeletal muscle, and FBXO32 is highly expressed in muscle tissue during muscle atrophy, upregulated in animal models of heart failure, and down-regulated in cardiac atrophy." (PMID 38455513, 2024).
melanoma (9 papers, 2016 to 2025). A malignant, usually aggressive tumor composed of atypical, neoplastic melanocytes. "Using loss of function approaches, we demonstrated that FBXO32 silencing in melanoma cell lines induced a downregulation of CDK6, a cell cycle protein promoting proliferation, and an upregulation of SMAD7, an inhibitor of the TGF-β pathway linked to cell migration." (PMID 33800394, 2021). "To further confirm that RAI14 affects c-MYC ubiquitination through FBXO32, we knocked down the expression of FBXO32 in RAI14 knockdown melanoma cells." (PMID 36233342, 2022). "We performed a comprehensive analysis of the role of FBXO32 in melanoma, showing that it regulates key biological processes and transcriptional programs of melanoma cells through epigenetics mechanisms." (PMID 33462405, 2021). "Conversely, forced FBXO32 expression using a lentiviral vector stimulated the migration of SKmel28 melanoma cell line." (PMID 33462405, 2021). "Transcriptomic analysis shows that FBXO32 knockdown induces a global change in melanoma gene expression profile." (PMID 33462405, 2021). "First, we analyzed FBXO32 expression in three melanoma cell lines and four short-term cultures derived from patients’ biopsies in our laboratory." (PMID 33462405, 2021). "The pro-tumoral function of FBXO32 was confirmed by biological studies demonstrating that FBXO32-forced expression favors proliferation and migration of melanoma cells, while FBXO32 downregulation has opposite effects." (PMID 33462405, 2021). "To do so, we performed a transcriptomic analysis in three different melanoma cell lines and one short-term culture (patient 2) treated with either control or FBXO32 siRNA." (PMID 33462405, 2021). "Here, we demonstrate that MITF regulates global ubiquitination in melanoma cells, at least in part, through FBXO32." (PMID 33462405, 2021). "In view to explore the biological functions of FBXO32 in melanomas, we studied the effect of FBXO32 silencing or forced expression on the motility of melanoma cells." (PMID 33462405, 2021). "In conclusion, our work establishes the role of MITF as a regulator of the ubiquitination pathway, in melanoma cells, through transcriptional regulation of several genes, among which FBXO32." (PMID 33462405, 2021). "This is consistent with the depletion of MKL in invasive breast cancer and melanoma cell lines, where the authors also observed an increase in Jun and FBXO32 RNA levels." (PMID 27600078, 2016). "F-box only protein 32 (FBXO32) is known to promote melanoma cell migration and proliferation." (PMID 40593126, 2025). "Additionally, FBXO32 knockdown in melanoma cells from patients inhibited their proliferation and migration." (PMID 37175415, 2023). "Knockdown of FBXO32, which is related to the metabolism of melanoma cancer cells, was able to induce global changes in melanoma gene expression profiles and was shown to correlate with melanoma cell migration, proliferation, and tumor development." (PMID 36338621, 2022). "Then, we showed that adenovirus-forced MITF expression led to an increase in FBXO32 protein expression in both 501MEL and A375 melanoma cell lines, while MITF silencing decreased the expression of FBOX32 and DCT, a known transcriptional target of MITF in MeWo and 501Mel cell lines." (PMID 33462405, 2021). "Taken together, these data demonstrate that FBXO32 enhances the migration of melanoma cells." (PMID 33462405, 2021). "Taken together these observations prompted us to investigate the role of FBXO32 in melanomas." (PMID 33462405, 2021). "Therefore, the transcriptional rewiring elicited by FBXO32 depletion in melanoma cells predicts an inhibition of proliferation and invasion, in agreement with the results of ours in vitro and in vivo functional studies." (PMID 33462405, 2021). "FBXO32 favors melanoma cell migration, proliferation, and tumor development in vivo." (PMID 33462405, 2021).
melanoma (continued). "Inhibition of FBXO32 expression ensuing MITF silencing was also verified by qPCR in 501Mel, MeWo, and two short-term melanoma cultures." (PMID 33462405, 2021). "Further analysis of the TCGA melanoma cohort showed that HERC5 and FBXO32 expression covaried with MITF; however, they were not correlated significantly with survival of patients with metastatic cutaneous melanoma." (PMID 33462405, 2021). "Very recently, our group identified FBXO32, a key component of the SCF ubiquitin- protein ligase complexes, as a MITF target, regulating melanoma cell migration and proliferation." (PMID 33800394, 2021). "FBXO32 and SMARCA4 are the components of a molecular cascade, linking MITF to epigenetics, in melanoma cells." (PMID 33462405, 2021). "Among them, we focused our attention on FBXO32 because it is located on chromosome 8q, a region frequently amplified in melanoma and its role in melanomas has never been studied." (PMID 33462405, 2021).
muscular dystrophy (8 papers, 2014 to 2024). Muscular dystrophy (MD) refers to a group of more than 30 genetic diseases characterized by progressive weakness and degeneration of the skeletal muscles that control movement. "It is worth noticing that miR-23a targets TRI63/MuRF and FBXO32/Atrogin-1 to suppress increased muscular dystrophy during cancer cachexia." (PMID 39404384, 2024).